TNF (tumor necrosis factor)
Diseases named in the same sentence as TNF in open-access papers (continued):
Sharing a sentence is not in itself a finding about the gene and the disease.
Sepsis (continued). "Indeed, in sterile sepsis models (i.e., LPS-induced shock), anti-TNF treated mice show some degree of protection but this is not recapitulated in real infection models such as cecal ligation and puncture (CLP)." (PMID 29751683, 2018). "Furthermore, NET inhibitor Cl-Ad suppressed the release of TNF-α and IL-1β in PLF after sepsis." (PMID 29789550, 2018). "TNF mediates inflammation in a classic “sepsis” cascade in tissues—in this pathway LPS from gram negative bacteria activates TNF release from cells, and then TNF stimulates production of IL-1b, IL-6, and IL-8, leading to neutrophil attraction into sites of infection." (PMID 30828428, 2018). "Therapeutic monoclonal antibodies targeting specific cytokines such as tumor necrosis factor-α (anti-TNF-α) have demonstrated mortality benefit in animal sepsis models and small scale human sepsis studies but have not succeeded in large scale pivotal trials in septic patients." (PMID 29084247, 2017). "In addition, we found higher serum levels of TNF-α in non-survivor as compared to survivor septic patients at days 4 and 8 of severe sepsis diagnosis." (PMID 28714876, 2017). "However, according to our experiments the higher level of TNF-α in sepsis serum is not the reason for impaired keratinocyte migration and wound healing, in contrast to previous studies." (PMID 28086962, 2017). "Increased levels of TNF-α in sepsis sera do not explain diminished keratinocyte migration." (PMID 28086962, 2017). "Increased concentrations of both proinflammatory (e.g., tumor necrosis factor [TNF], interleukin-6 [IL-6], and IL-8) and anti-inflammatory (e.g., IL-1Ra, IL-10, and high IL-10/TNF ratios) cytokines in patients with sepsis have been previously demonstrated to predict mortality." (PMID 27170644, 2016). "The release of IL-10 by PBMCs from septic patients was rather lower than that found in controls and patients with cured Q fever, suggesting that the decreased release of TNF in severe sepsis was not related to the overproduction of an immunosuppressive cytokine such as IL-10." (PMID 27441846, 2016). "Triggering inflammation by high levels of TNF-α may lead to tissue damage and, if not treated, to sepsis or death." (PMID 27150961, 2016). "TNF-α and IL-12 are typically pro-inflammatory cytokines and therefore, the observed suppression of these cytokines implies that NLP-31 and Y43C5A.3 may regulate inflammation during sepsis." (PMID 27672387, 2016). "Studies attempting to elucidate the hypothermic response in sepsis have focused on a hypothesized lack of proinflammatory cytokines, in particular interleukin (IL)-6 and tumor necrosis factor (TNF)-α, which are the main mediators of fever." (PMID 27737683, 2016). "Studies have shown that in TNF-α induced mouse systematic sepsis model, RIP3 is not directly involved in pro-inflammatory cytokines transcriptions, but could sustain their secretion indirectly by inducing cell necrosis which releases DAMP." (PMID 27195494, 2016). "Not surprisingly, in our TLR4+896A/G and CD14-159C/T variant alleles carriers with severe sepsis, increased TLR4 expression was accompanied by the up-regulation of in vitro LPS-stimulated NFκB, TNF-α, and iNOS signals on their cultured non-classical (CD16+, inflammatory) monocytes." (PMID 27861595, 2016). "In ONX 0914 treated mice we found elevated serum levels of creatinine and urea on day 7 and of TNF-α and IL-6 on day 3 and day 7 (data not shown) indicating that renal failure and sepsis might occur faster upon LMP7 inhibition." (PMID 26776888, 2016). "Interestingly, cytokines that are most commonly employed in experimental models of inflammation and/or sepsis (TNF-α, IL-1β, and IFN-γ) were not significantly increased in severe sepsis plasma obtained within 24 hours of ICU admission." (PMID 25882865, 2015).
Sepsis (continued). "However, clinical therapies targeting inflammatory cytokines such as tumor necrosis factor (TNF)-α and interleukin (IL)-1β antagonists have shown no benefit or, in some cases, have worsened survival, suggesting a complex pathological mechanism for sepsis." (PMID 25535255, 2015). "Secondly, in contrast to the decreased monocyte HLA-DR expression which has been proposed as a potential prognostic marker in patients with sepsis, we found variable HLA-DR expression which did not correlate with functional capacity to produce TNFα or clinical outcome." (PMID 26567164, 2015). "Thus, while TNF plays a role in the reduced T cell proliferative capacity after sepsis, neither the function of TNFR1 nor of TNFR2 alone solely accounts for this effect." (PMID 26734459, 2015). "In addition to attenuating the abrupt release of pro-inflammatory cytokines, including TNF-α, IL-1β and IL-6, treatment with chlorogenic acid enhanced serum Th1 cytokines during the late phase of sepsis without affecting Th2 cytokine release." (PMID 26063084, 2015). "Therapeutic effects of CORM-2 on sepsis-induced AKI were assessed by measuring serum creatinine (Scr) and blood urea nitrogen (BUN), kidney histology scores, apoptotic cell scores, oxidative stress, levels of cytokines TNF-α and IL-1β, and NLRP3 inflammasome expression." (PMID 26334271, 2015). "Recently developed drugs to fight sepsis, such as toll-like receptor 4 antagonists and tumor necrosis factor-α (TNF-α) antibodies, have also failed to decrease mortality or provide clinical benefit in large phase III studies, and thus there remains a need to develop better treatment strategies." (PMID 25887642, 2015). "However, other potential mechanisms in the pathophysiology of sepsis are likely, as previous studies of various anti-inflammatory agents, including TNF-α and IL-1 antagonists, showed little or no benefit in sepsis patients." (PMID 26121476, 2015). "Notably, a significantly higher level of TNF-α was found in sepsis patients (25.7 ± 18.6 vs. 57.6 ± 18.7 pg/ml, HC vs. sepsis, p < 0.001) than non-sepsis (25.7 ± 18.6 vs. 37.5 ± 16.8 pg/ml, HC vs. non-sepsis, p < 0.0001)." (PMID 26561011, 2015). "However, we need to be aware of SCLS and to diagnose it before using them, because these acute pharmacologic challenges are not established and a TNF-alpha antagonist is dangerous if patients have sepsis." (PMID 25928289, 2015). "We speculate that proinflammatory cytokines such as TNF-α, IL-1β, and IL-6 were released in the early stage of ALI challenge; in other studies, IL-6 was considered a particularly useful marker for prediction of the severity of sepsis." (PMID 25022445, 2014). "The study of proinflammatory cytokines IL-6, TNF-α, IL-1β, and IL-8 and anti-inflammatory cytokines IL-10 and TGF-β as reliable biomarkers of neonatal infection has been shown to be potentially useful for early sepsis diagnosis and to predict the severity of disease at early stages of the infection." (PMID 25614712, 2014). "Other authors showed that an in vivo sepsis not induced by LPS inhibits mTOR signaling pathways in rat cardiac muscle and that this defect appeared mediated, either directly or indirectly, by the endogenous over production of TNF-α." (PMID 25169902, 2014). "It has been found that α2-adrenoreceptor agonist might attenuate the increase in plasma level of IL-1β, TNF-α and improve survival successfully after caecal ligation and puncture (CLP)-induced sepsis, and reduce the incidence of sepsis-induced AKI by decreasing TNF-α and MCP-1." (PMID 23759023, 2013). "Interestingly, increase of TNF-α and IL-1β concentrations, but not IL-10 in plasma after administration of nociceptin has been also reported in a rat model with sepsis." (PMID 24066107, 2013). "Interestingly, whereas infection/sepsis-related mortality was not statistically different between these groups, only one cardiovascular death occurred in the high obestatin high TNF-α group." (PMID 24102059, 2013).
Sepsis (continued). "Thus, inhibition of GSK-3β could reduce the level of TNF-α and increase survival in the GAS-induced sepsis model." (PMID 23533310, 2013). "Also, at the time of diagnosis, IL-1beta, IL-6, IL-8, and TNF-alpha levels of culture-proven sepsis and culture-negative sepsis were significantly higher than levels at the seventh day after antibiotic treatment." (PMID 23869218, 2013). "Because splenocytes have been shown to exhibit decreased production of TNF and IFN-γ in non-alcoholic septic patients, this suggests that a more robust early pro-inflammatory response in mice with chronic alcohol ingestion may be maladaptive following sepsis." (PMID 23717394, 2013). "For example, HA-1A may improve outcomes in patients with gram-negative infections and anti-TNF-α therapies may effectively treat patients with elevated IL-6 levels despite these individual therapies' inability to treat all-comers with sepsis." (PMID 23251827, 2012). "Importantly, the absence of C5aR, NKT, and NK cells, but not of C5L2, led to significantly increased survival from sepsis, which was associated with reduced IFN-γ and TNF-α serum levels." (PMID 23233853, 2012). "The echocardiographic analyses revealed that 5HD could partially reverse sepsis-induced decreased cardiac output, ejections fraction and fractional shortening but did not affect systemic inflammatory response (TNF-alpha levels)." (PMID 21712982, 2011). "By contrast, in a study made in the ICU, although the plasma levels of TNF alpha were high in patients with septic shock, a correlation between TNF alpha levels and the severity of the sepsis could not be established." (PMID 21776298, 2011). "In light of our observation that administration of fetuin-A markedly reduced circulating levels of HMGB1, but not TNF-α (data not shown), we propose that fetuin-A confers protection against lethal endotoxemia and sepsis partly by inhibiting late mediators of these diseases." (PMID 21347455, 2011). "At admission to the ICU, serum suPAR concentrations in the total cohort and the subgroups of sepsis and non-sepsis patients were closely correlated to markers of inflammation and bacterial infection, as TNF-α (r = 0.571, P < 0.001), CRP (r = 0.411, P < 0.001) and PCT (r = 0.468, P < 0.001)." (PMID 21324198, 2011). "Sepsis-related release of TNF-alpha and liver tissue injury were not affected by Sepsis + TEA." (PMID 19594914, 2009). "So far, however, we could find only one report regarding the α2-AR subtypes responsible for TNF-α upregulation in pulmonary inflammation and none in sepsis itself." (PMID 19430535, 2009). "TNFα is a major contributor to sepsis, especially if not modulated by anti-inflammatory mediators." (PMID 19002259, 2008). "Since the PDI inhibitor bacitracin significantly increases TNF-α release in a macrophage cell line, it appears that prevention of PDI downregulation may be a novel approach to reduce proinflammatory cytokine release in sepsis." (PMID 18680601, 2008). "Although delayed administration of EGCG did not attenuate circulating TNF levels at 52 h after the onset of sepsis, it did significantly attenuate circulating levels of HMGB1 (P<0.05), suggesting that EGCG confers protection against lethal sepsis partly by attenuating systemic HMGB1 accumulation." (PMID 17987129, 2007). "The KEGG analysis results suggested that the differences between the two groups were mainly enriched in pertussis and TNF signaling pathway, demonstrating that hepatic GSDMD might play a role in the inflammatory response mediated by cytokines and secretory proteins in sepsis." (PMID 40856013, 2025). "Although previous clinical trials of TNF-α monoclonal antibodies have not shown overall benefit in unselected sepsis populations, our findings suggest that patient stratification into the inflammatory endotype might identify a subgroup more likely to benefit from these targeted therapies." (PMID 40448231, 2025).
Sepsis (continued). "Consequently, patients receiving TNF-α inhibitors may present with bacteremia or early sepsis in the absence of typical findings such as fever or leukocytosis, potentially delaying diagnosis and treatment." (PMID 41531628, 2025). "Therefore, we retrospectively selected 150 patients with sepsis admitted from January 2020 to January 2022, comprising 80 patients with SAE and 70 patients without, to examine the diagnostic value of serum TNF-α level combined with fecal calprotectin level for early SAE." (PMID 40529149, 2025). "Thus, the serum levels of TNF-α and IL-6 have been proposed as prognostic parameters for patients suffering septic shock, and immunotherapy using anti-TNF-α or anti-IL-6 monoclonal antibodies, such as afelimomab and tocilizumab, have reduced overall mortality from severe sepsis." (PMID 36675101, 2023). "When incubated for 6 hours without extrinsic stimuli, whole blood from sepsis patients, which already contained greater inflammatory cytokine concentrations than that of healthy volunteers, showed a significant further increase of supernatant TNF, IL-6, IL-8, IL-1α, and IL-1β concentrations." (PMID 37869001, 2023). "Importantly, we found that DMF also inhibited the LPS-induced cytokine production in LPS-stimulated RAW264.7 cells, including IL-6, G-CMF, TNF-α, and MCP-1, suggesting that DMF may have the potential to treat various inflammation-related diseases including sepsis." (PMID 37840694, 2023). "Among them, several of the classical inflammatory markers, e.g., IL6, IL8, IL10, IL12B, TNF, and IFNγ had substantially higher levels in sepsis compared to COVID-19, leading to the conclusion that the inflammatory response is more pronounced in sepsis regardless of etiology or focus of infection." (PMID 36829233, 2023). "The results showed that IL-1β, IL-6, and TNF-α contents of model group increased markedly vs. control and interference groups, suggesting that IL-17RA-1 might promote the secretion of proinflammatory factors by THP-1-M1 cells, contributing to the development of sepsis." (PMID 36274974, 2022). "Interestingly, it was recently shown that LPS challenge did not induce a TNF response in models of post-sepsis survival (i.e., animals surviving a septic episode that exhibit persistent immune impairment and immune fatigue, or compensatory anti-inflammatory response syndrome)." (PMID 35784337, 2022). "In addition, podophyllotoxin can also rapidly inhibit cytokine secretion by PBM after their activation via multiple stimuli including LPS and IFN-γ, whereas currently no specific treatment targeting inflammation was effective in sepsis shock, neither were antibodies targeting TNFα, IL-1, and LPS." (PMID 34804111, 2021). "However, antibody drugs targeting cytokines (e.g., tumor necrosis factor [TNF] and interleukin 6 [IL6]), inflammatory pathways (e.g., toll like receptor 4 [TLR4]), or endotoxin, as well as empiric antibiotic therapies have little or disappointing benefit for patients with sepsis." (PMID 33776776, 2021). "Additionally, we analyzed selected plasma cytokines (tumor necrosis factor (TNF)-α, Interferon (IFN)-γ, Interleukin (IL)-1β and IL-6) and bacterial infection burdens as well as changes in the peritoneal microbiome in experimental animals with CASP-induced sepsis." (PMID 33466819, 2021). "Therefore, the effect of CaD to decrease CD14 and TLR4 expression could offer one mechanism to explain why CaD inhibits NF-κB and suppresses the release of downstream NF-κB activation products—TNFα, IL-1β, IL-6, and MCP-1 in animal models of sepsis and diabetic nephropathy and retinopathy." (PMID 34829669, 2021). "Studies have reported that cytokines (TNF-α, IL-10, and TGF-β) could regulate apoptosis by regulating the activity of caspase-8 in the death-induced signaling complex or changing death or survival factor levels, which control the Fas apoptotic pathway in sepsis." (PMID 33954185, 2021).
Sepsis (continued). "However, this combination may not be applicable in vivo because high dose of TNF may evoke a strong inflammation leading to sepsis and multiple organ dysfunction." (PMID 33542218, 2021). "Moreover, previous studies of sepsis and ALI have demonstrated that HIF-1α expression may induce acute lung epithelial damage and the production of numerous proinflammatory cytokines such as IL-6, MIP-2 and TNF-α via the nuclear factor-κB (NF-κB) pathway." (PMID 32353952, 2020). "We here demonstrate that blood leukocytes of hospitalized CAP patients display an impaired release of TNF-α, IL-1β, IL-6, and IL-10 as well as an heightened production of IL-1RA in response to stimulation with LPS and K. pneumoniae, regardless of the presence of sepsis." (PMID 32477337, 2020). "There may be no magic target to cure sepsis, and a combined approach could be more beneficial than targeting a single molecule, as shown for IL‐1 and IL‐18 in murine sepsis, IL‐1 and TNF in a rat model, or CD14 and factor XIa in rabbits." (PMID 32176432, 2020). "Although the experimental model of infectious disease (e.g., malaria and sepsis) and autoimmune disease (e.g., RA and SLE) indicates that artemisinin-family drugs could target the inflammatory networks to decrease the levels of cytokines (e.g., IL-6 and TNF-α) and chemokines (e.g., IL-8, CXCL10)." (PMID 32754163, 2020). "However, blood samples from sepsis patients need to be tested for IRAK3, TNF-α and IL-6 protein levels at more time intervals after endotoxin challenge to clarify whether the patterns of temporal expression of these molecules reflect in vitro human cell culture models." (PMID 33382782, 2020). "Currently available treatments for sepsis, such as antibacterial therapy using antibiotics, infusion therapy with donor fresh frozen plasma, and therapies that alleviate hypercytokinemia by decreasing levels of cytokines [particularly tumor necrosis factor (TNF)-α], are not successful in all cases." (PMID 29795607, 2018). "Whether or not elevated TNF-α is detrimental in sepsis remains controversial." (PMID 28105603, 2017). "However, unlike other sepsis studies which showed that pro-inflammatory cytokines like IL-1ß and TNF-α could predict mortality, this study did not confirm such a relationship." (PMID 28320333, 2017). "Thus, the presence of other diseases may influence the genetic role of TNF-α rs361525, but not TNF- rs1800629 in sepsis risk." (PMID 29340067, 2017). "Mediators of sepsis such as lipopolysaccharide (LPS), a gram-negative bacterial cell wall component, triggers apoptosis in cardiac myocytes by promoting the secretion of cytokines such as tumor necrosis factor α (TNF-α), interleukin-6 (IL-6), IL-10, and interferon (IFN)-γ." (PMID 26659076, 2016). "Several studies demonstrate that the protective role of MSCs in sepsis may be attributed essentially to the soluble paracrine factors released by these cells, such as interleukin-10 (IL-10), prostaglandin E2 (PGE2), tumor necrosis factor-alpha (TNF-α)-stimulated gene/protein 6, and IL-6." (PMID 26474552, 2015). "In addition, TNF-α and IL-1 amplify inflammatory cascades in an autocrine and paracrine manner by activating macrophages to secrete other proinflammatory cytokines (IL-6, IL-8, and MIF), lipid mediators, and reactive oxygen and nitrogen species, leading to sepsis-induced organ dysfunction." (PMID 23853427, 2013). "In addition, our data show that the effect of TNF-α on lung inflammation and AKI occurs rapidly as prophylactic anti-TNF-α treatment was effective to reduce lung inflammation and kidney dysfunction, but anti-TNF-α treatment administered just two hours after the onset of sepsis was ineffective." (PMID 24265742, 2013). "In this context, while neutralization of TNF-α had been shown to be protective in animal models of TSS, clinical studies have shown that antagonizing the biological functions of TNF-α is ineffective during sepsis/TSS in human patients and might even be counter productive." (PMID 21304813, 2011).